TPM3 (tropomyosin 3)
Diseases named in the same sentence as TPM3 in open-access papers (continued):
Sharing a sentence is not in itself a finding about the gene and the disease.
tumor (continued). "Further investigation on clinicalspecimen demonstrated GEP and TPM3 to be overexpressed in HCC compared withnon-tumor liver sample, and the expression levels of GEP and TPM3 were significantlycorrelated." (PMID 22792281, 2012). "The model includes seven key genes—SNX5, YBX1, GNPD1, RAB32, TPM3, ATP6V0B, and RAB7A—which may be involved in tumor growth, immune escape, and microenvironment remodeling and may serve as potential targets for therapy." (PMID 41031219, 2025). "Tumor cells also recruit platelets into the tumor microenvironment (TME), and platelets are activated by tumor cells to release the cytokines VEGF, CCL5, PDGF, TGFβ, PG, TPM3, LPA, PF4, PAF, and HGF, which promote the epithelial-mesenchymal transition of tumor cells." (PMID 35836573, 2022). "Treatment with 0.3 mg/Kg of Pz-1 was able to completely block NIH3T3 NCOA4-RET but not TPM3-TRKA tumour growth." (PMID 34373541, 2021). "Given the role of TPM3 in promoting the invasion of tumor cells, we examined whether the effect of platelet‐releasing microvesicles from patients with BC on the invasion of MDA231 cells was TPM3 dependent." (PMID 31705785, 2019). "Protein expression of TPM3 was investigated by immunohistochemical staining,and TPM3 protein was observed only in tumor tissues but not in the non-tumoroustissues.The staining patterns of GEP and TPM3 were compared." (PMID 22792281, 2012). "IMT is the tumor that most frequently overexpresses ALK protein, however, in addition to no expression of skeletal muscle markers Myo-D1, Myogenin and Myogenin, genetically, IMT usually shows ALK re-arrangement with many other molecular partners including TPM3, KIF5B, CARS, and THBS1." (PMID 36998041, 2023). "At the end of tumour growth experiment, phosphorylation of NCOA4-RET G810R and TPM3-TRKA G595R confirmed their strong resistance to Pz-1, with only NCOA4-RET G810R showing some rate of inhibition at the highest used dose (3 mg/Kg), possibly explaining the partial tumour growth inhibition." (PMID 34373541, 2021).
cancer (30 papers, 2009 to 2025). A tumor composed of atypical neoplastic, often pleomorphic cells that invade other tissues. "There is more and more evidence that overexpression of TPM3 is strongly associated with cancer occurrence and progression." (PMID 37686101, 2023). "IncreasedGEP levels were associated with cancer recurrence, thus theassociation of TPM3 with recurrence-free survival was examined." (PMID 22792281, 2012). "Because Tpm3.1/3.2 has been implicated in cancer progression and the Tpm3 gene is overexpressed in many cancers, including DLBCL, we hypothesized that Tpm3.1/3.2 could be a target for treating DLBCL." (PMID 41268543, 2025). "TEP TPM3 mRNA was significantly increased in breast cancer patients, with its transfer into cancer cells mediated by platelet-derived particles to promote cancer cell migration." (PMID 37139159, 2023). "Previous studies have identified the key role of TPM1–4 in some cancers, especially the role of TPM3 and TPM4 in HCC development." (PMID 34850589, 2022). "Upregulated PCBP1 led to significant upregulation of TPM3 in cancer tissues by directly binding to TPM3 mRNA and enhancing its mRNA stability, promoting migration and invasion of ESCC cells." (PMID 35287546, 2022). "In this study, we found that platelet TPM3 (tropomyosin 3) mRNA can be delivered into cancer cells via microvesicles to promote cancer cell migration." (PMID 31705785, 2019). "TPM3 expression has been reported to control migration, invasion, and anchorage-independent growth of cancer cells by modifying the epithelial-mesenchymal transition pathway." (PMID 31810358, 2019). "It should also be noted here that TnT’s binding partner in striated muscle cells, e.g., α-Tm (TPM3), is also overexpressed in cancers of the breast, endometrium, cervix, liver, and esophagus." (PMID 29416706, 2018). "The potential involvement of Tm in these proposed mechanisms is consistent with the findings of TPM3 overexpression in online cancer databases." (PMID 29416706, 2018). "Importantly, this work represents the first comprehensive effort to integrate findings across all reported TPM3 fusion partners and cancer types, with the goal of establishing a unified biological and clinical paradigm that has been lacking in the literature." (PMID 41275415, 2025). "Overexpressed tropomyosin 3 isoform 2 (TPM3) is related to cancer progression and metastasis." (PMID 38249992, 2024). "TPM3 is the major isoform in cancer cells, accounting for 70% of the total tropomyosin." (PMID 37176055, 2023). "In summary, our findings suggest that the transfer of platelet TPM3 mRNA into cancer cells via microvesicles promotes cancer cell migration, and thus platelet‐derived TPM3 mRNA may be a suitable biomarker for early diagnosis of metastatic BC." (PMID 31705785, 2019). "By transwell assay, we also revealed that the TPM3 mRNA delivered by platelet‐derived microvesicles could be translated into proteins in the cancer cells and promote invasion." (PMID 31705785, 2019). "Taken as a whole, our data suggest that upregulation of Tpm3 is a cancer-related event, and underscores the need for further studies to assess the clinical validity and utility of this protein as a biomarker for the early detection of cancer." (PMID 31810358, 2019). "According to our observations, we then aimed to determine whether the invasion of MDA231 cells was enhanced by transferring the TPM3 mRNAs into cancer cells through platelet‐releasing microvesicles." (PMID 31705785, 2019). "Gene fusions such as TPM3—NTRK1, TPM3—ALK, and TPM3—ROS1 have been identified as oncogenic drivers in various cancers." (PMID 41275415, 2025). "Among these cancers, ALK gene fusions were identified to be most common in ALCL (60% cases, mainly NPM-ALK fusion), followed by IMT (~50% cases, mainly TPM3/4-ALK fusion), NSCLC (~5–7% cases, mainly EML4-ALK fusion), and other cancers." (PMID 32059449, 2020).
cancer (continued). "To date, several more ALK hybrid proteins have been identified in various cancer types, such as TRK-fused gene (TFG)-ALK, tropomyosin 3 (TPM3)-ALK, tropomyosin 4 (TPM4)-ALK, clathrin heavy chain-like 1 (CLTCL1)-ALK, and moesin (MSN)-ALK." (PMID 23667670, 2013). "However, the association of GEP with TPM3 high molecular weight isoformin other cancer types could not be excluded because these isoforms have significantconserved sequences." (PMID 22792281, 2012). "This ongoing research into the molecular mechanisms of TPM3‐ALK fusions and their role in cancer pathogenesis continues to provide valuable insights into potential therapeutic strategies and the development of more effective treatments for patients with ALK‐rearranged tumors." (PMID 41275415, 2025). "In a similar study of NTRK fusions in cancer patients, those harboring fusions with any of the 3 most frequent partners ETV6, TPM3, and LMNA comprised 22.3% (198/889) of all NTRK‐positive cases, a percentage closer to our observation with MET (13/122 patients, 10.7%)." (PMID 37326363, 2023). "Theliver cancer cells and clinical samples showed low/undetectable transcriptlevels of TPM3 high molecular weight isoform 1 (data not shown)." (PMID 22792281, 2012). "To explore the potential mechanisms of reduced migration and invasion in TPM3 knockdown HCC cells, we examined the expression patterns of E-cadherin and Snail, a known factor to repress E-cadherin expression by binding to E-boxes of the E-cadherin promoter in cancers." (PMID 20356415, 2010). "We further examined the expression of Snail in TPM3 knockdown HCC cells showing upregulated E-cadherin, because the Snail transcription factor has been known to repress E-cadherin expression by binding to E-boxes in the E-cadherin promoter in cancers including HCC." (PMID 20356415, 2010).
myopathy (20 papers, 2011 to 2025). A disease of the muscle in which the muscle fibers do not function properly. "There exists a pressing need to improve the diagnosis of TPM3-related myopathy, understand the molecular causes of the disease, and develop adequate treatments for the patients." (PMID 37936227, 2023). "To gain insight into the regulation of cofilin-2 activity by a myopathy-causing mutation in TPM3, we used the p.R91C substitution in Tpm3.12, which is associated with muscle weakness in patients and causes the hypocontractile phenotype in vitro." (PMID 38003645, 2023). "The use of different in vitro and in vivo model systems has leveraged the discovery of several disease mechanisms associated with TPM3-related myopathy." (PMID 37936227, 2023). "We then analyzed how the myopathy-causing Tpm3.12 variant changes the interactions of cofilin-2 with actin filament." (PMID 38003645, 2023). "Variants in one of the two tropomyosin genes, TPM2 and TPM3, have been associated with a number of different myopathies." (PMID 35052370, 2021). "Although some TPM3 variants are associated with a specific form of myopathy, the fiber-type distribution pattern and the pattern of protein inclusions often vary widely, even among patients with the same TPM3 mutation." (PMID 33652732, 2021). "Both SEPN1 and RYR1 were excluded, as were ACTA1 and TPM3, in which mutations cause congenital fiber type disproportion, a myopathy clinically similar to MmD." (PMID 22371254, 2012). "TPM3 has been linked to myopathy, and a dominant negative mutation of TPM3 causes muscle weakness." (PMID 39559755, 2024). "A study revealed Muscle weakness in TPM3-myopathy is due to reduced Ca2+ -sensitivity and impaired acto-myosin cross-bridge cycling in slow fibers." (PMID 38704563, 2024). "In TPM3-related myopathy, patients commonly develop static to slowly progressive muscle weakness in one or several muscle groups." (PMID 37936227, 2023). "In TPM3-related myopathy, the presence of protein aggregates is limited to small type 1 fibers and are often, if not always, associated with excessive fiber size variation (also known as fiber size disproportion)." (PMID 37936227, 2023). "We compared the exon-exon junctions in TPM3 in RNA-seq data of the patient with an internal control group (RNAseq data from muscle of over 200 myopathy and non-myopathy individuals)." (PMID 37393515, 2023). "In this review, we will provide an update on TPM3 function in skeletal muscle and the current state of TPM3-related myopathy." (PMID 37936227, 2023). "Here, we will discuss recent findings about the effects of TPM3 mutations on muscle function, providing new perspectives on the mechanisms that contribute to TPM3-related myopathy and the development of therapeutic strategies." (PMID 37936227, 2023). "Currently, there is no cure for TPM3-related myopathy, and treatment is supportive and based on the individual's specific symptoms and needs." (PMID 37936227, 2023). "In the mid-1990s, TPM3-related myopathy was first described as nemaline myopathy 1 (NEM1) in an Australian family." (PMID 37936227, 2023). "In comparison with NM patients who have the typical form, a few clinical features, similar to those in our patient, appear distinct among patients with recessively inherited TPM3 myopathy." (PMID 37393515, 2023). "Since then, several case reports have been published, yet the molecular mechanisms responsible for TPM3-related myopathy remain poorly understood." (PMID 37936227, 2023). "Since then, the identification of several patients and families affected by TPM3-related myopathy revealed a broader range of pathological features in muscle biopsies." (PMID 37936227, 2023).
myopathy (continued). "A high degree of phenotypic diversity and intrafamilial variability has been observed in TPM2- and TPM3-related myopathies." (PMID 32456280, 2020). "Despite the fact that Met9Arg TPM3 nemaline myopathy mice are reported to have delayed maturation on the basis of perturbed muscle fibre-type proportions, internally-nucleated fibres have not been observed." (PMID 22174871, 2011). "Animal models leveraged the discovery of secondary mechanisms related to TPM3-related myopathy." (PMID 37936227, 2023). "No clear relationship has also been established between the diagnosis and disease severity or disease onset as a distinct diagnosis can be made among family members affected by TPM3-related myopathy as well as in different muscle biopsies taken from a same individual." (PMID 37936227, 2023). "TPM3-related myopathy was first described in a large Australian family in 1992." (PMID 37936227, 2023). "The clinical spectrum of TPM3-related myopathy is broad, ranging from mild to severe presentations." (PMID 37936227, 2023). "For years, the study of TPM3-related myopathy received little attention." (PMID 37936227, 2023). "Open-source databases, patient registries, and variants of unknown significance (VUS) were not considered in this review, and therefore the number of patients affected by TPM3-related myopathy is likely to be underestimated." (PMID 37936227, 2023). "While some may exhibit generalized muscle weakness, others might display more localized weakness in axial, proximal, or distal muscles, which could partially contribute to the broad spectrum of clinical manifestations observed in TPM3-related myopathy." (PMID 37936227, 2023). "Various myopathies are known to be caused by this decoupling mechanism and result from variants in other skeletal muscle genes involved in the Ca2+-dependent contraction response, including TPM2, TPM3, and ACTA1." (PMID 32819427, 2020). "Furthermore, compounds used in slow, type 1 muscle fibers target both cardiac and slow skeletal isoforms, and the effect on cardiac function in the context of TPM3-related myopathy is still unknown." (PMID 37936227, 2023). "The degree of protein aggregates observed in muscle biopsies and among patients with TPM3-related myopathy varies significantly, and there exists no evident correlation with disease severity." (PMID 37936227, 2023).
infection (7 papers, 2013 to 2024). The state of being infected such as from the introduction of a foreign agent such as serum, vaccine, antigenic substance or organism. "Age-declining genes include metabolic regulators of glycosylated surface proteins and lipids, like Slc35a1115 and Gale116, important for immune recognition and pathogen infection, expressed in TAs and goblets, and Tpm3, a gene recurrently lost in CRC117, expressed in ISCs." (PMID 38712088, 2024). "The significantly downregulated genes (NEAT1, TPM3, ZNHBA, CKLF, and OSBPL8) and the upregulated genes (ITMZC, IFNG, CD69, DNAJB9, and LYST) in NCAM1+FCGR3A+dNK cells after infection were also analyzed." (PMID 38730500, 2024). "Expression of CMA genes during infection of these cell lines was also examined (right 12 lanes), and demonstrated that reduction in GRIM-19 level did not influence the level of transcription of any of the four CMA genes tested (TPM3, STX3, Dystroglycan 1 [DAG1], and Heme-binding protein 1 [HEBP1])." (PMID 34346763, 2021).
adenocarcinoma (2 papers, 2017 to 2024). A common cancer characterized by the presence of malignant glandular cells. "Four top performing EV-associated proteins that distinguished adenocarcinoma cases from controls, SRGN, TPM3, THBS1 and HUWE1, yielded a combined area under the receiver operating characteristic curve (AUC) of 0.90 (95% CI = 0.76-1)." (PMID 29221141, 2017).
muscular disorders (2 papers, 2021 to 2025). "The causative mutations found in TPM3 and SELENON—genes associated not only with MFM—highlight the phenotypic heterogeneity and clinical overlap between muscular disorders." (PMID 33652732, 2021).
movement disorder (1 paper, 2021). Neurological conditions resulting in abnormal voluntary or involuntary movement, which may impact the speed, fluency, quality and ease of movement.
TPM3 also shares sentences with these, for which no sentence is quoted: lung cancer (9 papers); spindle cell sarcoma (4); anaplastic large cell lymphoma (3); centronuclear myopathy (3); glioblastoma (3); melanoma (3); glaucoma (2); ulcerative colitis (2); arthrogryposis (1); astrocytoma (1); atrial fibrillation (1); autism spectrum disorder (1); autoimmune hepatitis (1); autosomal dominant macrothrombocytopenia (1); cardiac disease (1); cholangitis (1); chromosomal disorder (1); chronic kidney disease (1); chronic lymphocytic thyroiditis (1); colitis (1); congenital fibre type disproportion (1); congenital nemaline myopathy (1); Crohn disease (1); diabetic cardiomyopathy (1); distal myopathy (1); Ewing sarcoma (1); Failure to thrive (1); Gorlin syndrome (1); limb-girdle muscular dystrophy (1); lymphoma (1).
A further 27 diseases each share a sentence with TPM3 in 1 paper.